LINC02166 (long independently transcribed non-coding RNA 2166)
Gene: Long non-coding RNA gene on chromosome 16 (89,682,506 to 89,686,921, reverse strand). Ensembl gene ENSG00000260259.
Diseases named in the same sentence as LINC02166 in open-access papers:
LINC02166 is named in the same sentence as 1 disease in open-access papers, as found by Europe PMC text mining. Sharing a sentence is not in itself a finding about the gene and the disease. The quoted sentences say what the papers report.
breast carcinoma (2 papers, 2021). "In conclusion, we identified a novel autophagy‐related prognostic risk model consisting of 11 lncRNAs (U62317.4, LINC01016, LINC02166, C6orf99, LINC00992, BAIAP2‐DT, AC245297.3, AC090912.1, Z68871.1, LINC00578 and LINC01871) in breast cancer." (PMID 33216456, 2021). "The predicting value of 11 sARLNRs (U62317.4, LINC01016, LINC02166, C6orf99, LINC00992, BAIAP2-DT, AC245297.3, AC090912.1, Z68871.1, LINC00578, and LINC01871) was also identified in breast cancer." (PMID 34414116, 2021).